AQP4 (aquaporin 4)
Diseases named in the same sentence as AQP4 in open-access papers (continued):
Sharing a sentence is not in itself a finding about the gene and the disease.
Stroke (continued). "However, so far little research has been done about the change of AQP4 polarization and the relation between AQP4 and DG in vivo after TBI, which affects twice as many patients as stroke injury." (PMID 26583111, 2015). "We also showed that the upregulation of AQP4 in a preconditioning model did not prevent the early opening of the BBB after stroke." (PMID 22778741, 2012). "AQP4 expression is elevated in many conditions of CNS inflammation and diseases such as spongiform encephalopathy, Alzheimer's, stroke and others which do not have an infection or autoimmune component." (PMID 18510734, 2008). "However, our results showed a lower expression of AQP4 on day 4 in rats treated with both doses of Neuroncell-EX compared to the stroke control, but the difference was not statistically significant." (PMID 40360812, 2025). "Another putative molecule important in maintaining CSF and ISF exchange is the water channel aquaporin 4 (AQP4) and there is evidence to indicate that, while the abundance of AQP4 does not appear to be altered after stroke, the location of AQP4 in the lipid membrane of astrocytes is changed." (PMID 40533800, 2025). "In the context of regeneration, it is interesting to note that Aqp4−/− mice have deficits in synaptic plasticity and spatial memory formation, indicating a possible role for AQP4 in the formation and tuning of the new synapses that are generated during recovery from stroke or TBI." (PMID 37702572, 2024). "Recently, caveolin‐1 knockout was found to reduce AQP4 expression in a mouse stroke model, although it is not clear whether this was due to a direct role of caveolin‐1 in AQP4 internalisation, or a secondary effect on AQP4." (PMID 38102893, 2024). "Lack of specific and therapeutic pore‐blocking AQP4 inhibitors highlights the need to explore alternative routes to control the water permeability in glial cell membranes that facilitate brain swelling following insults, such as traumatic injury or stroke." (PMID 38102893, 2024). "The present work therefore analyses whether or not periinfarct astrogliosis and AQP4 depolarization are suppressed by hypoxic microglia-derived EVs under stroke conditions." (PMID 37554272, 2023). "Interestingly, the endfoot membrane of AQP4 was increased, but the total protein levels of it had no changes, implying that the relocalization of this molecule occurred under stroke and traumatic brain injury." (PMID 36769234, 2023). "Several studies have theorised the use of AQP4 therapies in several conditions, such as stroke and AD; but no specific human trials utilising AQP4 treatments for these have yet to be conducted from the date of this review and the exact mechanism of this remain complex and not fully comprehended." (PMID 36498538, 2022). "However, the direct assessment of the AQP4 content in the blood serum has not been proved as useful for stroke diagnosis." (PMID 31701356, 2020). "However, AQP4 is not involved in gender-specific differences in stroke volume and finally, the perivascular pool of AQP4 does not alter after ischemic stroke." (PMID 31178701, 2019). "In particular, Human Aquaporin 4 (h-AQP4) is abundantly expressed in blood–brain and brain–cerebrospinal fluid interfaces, and is responsible for homeostasis of cerebral water; its function is related to neuropathological disorders such as brain edema, stroke and head injuries." (PMID 27428954, 2016). "Changes in AQP4’s glycosylation state under hypoxic or inflammatory conditions could, therefore, alter how much functional channel resides at the membrane, although direct evidence in stroke models remains lacking." (PMID 40943104, 2025). "We subsequently explored whether the amount of AQP4 and GDNF in the EV cargo correlated with the severity of neurological deficit, assessed by the NIHSS score at D1, D7, and M1, or with the short-term outcome according to the mRS score at D7 and M1 following stroke onset." (PMID 39596535, 2024).
Stroke (continued). "Thus, AQP4 is not just a passive participant in post‐stroke neuroinflammation but may actively modulate the dynamics and outcomes of the inflammatory response." (PMID 39444081, 2024). "Moreover, given the fact that stroke represents a rather heterogenous syndrome, a combined panel incorporating BNP, GFAP, RDW, NLR, MMP-9, and AQP4 might represent a promising approach, both in research and in clinical practice, minimizing the effect of any individual biomarker." (PMID 36278689, 2022). "It is clear that post-stroke exposure to LOPC promotes neuronal survival and vascular growth, yet what remains unclear is whether LOPC improves other aspects of vascular function (i.e., AQP4 polarization), or whether these improvements can modulate the Aβ burden." (PMID 33841293, 2021). "However, although 70% maximal inhibition of rat AQP4 and 20% maximal inhibition of mouse and human AQP4 have been reported in water transport assays, AER-270 had the same effect on water content in rat and mouse stroke models, suggesting that the effect is not AQP4 dependent." (PMID 32413299, 2020). "In order to investigate whether there are some common pathological links in stroke and AD, we used the suture method to block the middle cerebral artery and simulate stroke, and observed the expressions of the characteristic protein Aβ, its precursor APP and AQP4 after CIRI." (PMID 33817204, 2019). "Up-regulation of AQP4 water channels, for example, tracks with edema severity after stroke and TBI, but blocking AQP4 in humans has not reproduced the benefits seen in rodents—underscoring how cytotoxic and vasogenic edema differ across diagnoses and species." (PMID 40771971, 2025). "In stroke models and TBI aqp4−/− mice did not exhibit elevated brain water content, confirming the connection between cerebral edema and AQP4." (PMID 35163313, 2022). "As observed for AQP4-labeling, there was no change in the length of GFAP-positive branches in Cav-1 KO stroke mice compared to sham." (PMID 32523952, 2020). "AQP4 levels increased at the astrocyte cell surface despite no changes in total protein expression, suggesting that relocalization of the channel occurred after traumatic brain injury (TBI), infections, tumor growth, or stroke, which could exacerbate brain swelling." (PMID 35163313, 2022).
brain edema (171 papers, 2007 to 2026). Increased intracellular or extracellular fluid in brain tissue. "Cerebral ischemia/reperfusion can cause and aggravate cerebral edema by increasing the expression of Aquaporin-4 (AQP4), a water channel protein closely associated with cerebral edema formation." (PMID 40353059, 2025). "Studies using AQP4 knockout mice, or AQP4 inhibition, have shown that with some injuries, the loss of AQP4 function can lead to the reduced development of cerebral oedema." (PMID 40869387, 2025). "Taken together, these clinical data consistently point to AQP4 as a central mediator of cerebral edema in TBI, with expression changes tightly linked to inflammatory signaling (e.g., IL-6, TLR4), hypoxia, and axonal damage." (PMID 40564125, 2025). "In the central nervous system, AQP1 and AQP4 have long been associated with the pathophysiology of cerebral edema, and AQP4 contributes to the formation and regression of edema after spinal cord injury." (PMID 39637010, 2024). "Fourth, further studies are needed to define the role of aquaporin-4 or other channels for water movement that underlie the development of radiographically detectable cytotoxic cerebral edema early after CLP." (PMID 36681815, 2023). "Single nucleotide polymorphisms (SNPs) in the AQP4 gene are associated with both seizure susceptibility, epilepsy, and the development of brain edema." (PMID 36735187, 2023). "Both gain-of-function and loss-of-function gene variants are present in the AQP4 gene, including an association between rs9951307 and severe brain edema in patients with middle cerebral artery occlusion." (PMID 36735187, 2023). "For SIDS cases that are carriers of several specific AQP4 variant genotypes (CT/TT, rs2075575), an increased brain-to-body weight ratio was found, and thus a putative association of AQP4 variants and cerebral edema in SIDS." (PMID 35474489, 2022). "In conclusion, our findings revealed altered levels of TNFα, Kir 4.1, GFAP, and AQP4 in HE-associated brain edema." (PMID 36060277, 2022). "Cerebral edema is primarily an intracellular water accumulation process, caused by water influx through AQP4 passively in response to osmotic gradients, and usually as a consequence of ischemia-hypoxia." (PMID 35370910, 2022). "Brain edema is caused by the proteins aquaporin 4 (AQP4), metalloproteinase 9 (MMP9), and vascular endothelial growth factor (VEGF)." (PMID 35741689, 2022). "The AQP4-deficient mice are relatively safe from water influx during cytotoxic edema development, however they show worsened outcome of vasogenic cerebral edema, because the water drainage from brain parenchyma is compromised." (PMID 36568889, 2022). "AQP4 is abundantly distributed in the brain and responsible for water exchange across the BBB and maintenance of ion homeostasis; aberrant AQP4 expression was reported to be associated with cerebral edema/ischemia." (PMID 36335301, 2022). "TBI-associated brain edema is connected with increased expression of aquaporin-4 at the site of injury; however, how aquaporin-4 contributes to the pathology is not known." (PMID 33505713, 2021). "The role of glial AQP4 in brain water homeostasis has been characterized by the team of Verkman, who showed that AQP4−/− mice had improved survival and less cerebral edema than wild-type mice in a model of brain edema caused by acute water intoxication." (PMID 30841618, 2019). "In contrast, loss of AQP4 was harmful in multiple models of brain edema, and chronic brain injury was aggravated in AQP4 null mice after focal cerebral injury." (PMID 31187032, 2019). "It is known to play a critical role in BBB integrity, and increased AQP-4 expression has been linked to various types of cerebral edema." (PMID 30814927, 2019). "As to patient studies, one study on polymorphism in AQP4 genes suggests AQP4 gene variant, single nucleotide polymorphism (SNP) rs1054827, is independently associated with brain edema after ICH." (PMID 27529222, 2016).
brain edema (continued). "AQP4 has been implicated in various neurological disorders such as epilepsy, cerebral edema, and Alzheimer’s disease." (PMID 26941623, 2016). "High AQP4 levels were associated with high neurological deficit and presented a positive correlation with brain edema." (PMID 26039099, 2015). "Mice deficient in AQP4 have much better survival than wild-type mice in a model of brain edema caused by acute water intoxication." (PMID 20815926, 2010). "Additionally, Papadopoulos and Verkman (2005) reported that AQP4-deficient mice had significantly less brain water accumulation in meningitis-induced brain edema, another cytotoxic edema model." (PMID 39944892, 2025). "Although AQP4 may cause cerebral oedema, it is also responsible for oedema clearance, and therefore chronic depletion may result in broad detrimental outcomes for recovery and healthy development." (PMID 40375338, 2025). "Additionally, AQP1 and AQP4 can help predict post-burn or post-traumatic cerebral edema, and genetic mutations in AQP1 and AQP9 can indicate the risk of SIDS." (PMID 38473914, 2024). "Indeed, a recent study showed that traumatic brain injury-induced cerebral edema is associated with increased expression of aquaporin 4 (AQP4) and vasopressin 1a receptor and astrocytic swelling." (PMID 28008305, 2016). "However, acceleration of trauma-related cerebral edema by ethanol has been linked to increased AQP4 upregulation and activity, with acetazolamide, presumably through inhibition of AQP4, exerting protection." (PMID 25029343, 2014). "ADC values represented water movement within tissues and increased values are thought to be associated with excess extracellular fluid accumulation secondary to BBB disruption caused by brain injury; AQP4-mediated transcellular water movement is crucial for fluid clearance in vasogenic brain edema." (PMID 24282821, 2013). "In particular the MCAO-induced overexpression of cerebral AQP4 can be greatly reduced by agmatine therapy, suggesting that the enhanced water movement associated with the pathophysiology of cerebral edema after transient cerebral ischemia is attenuated by agmatine." (PMID 20815926, 2010). "AQP4 in cerebral microglia may contribute to the pathogenesis of cerebral edema, as AQP4 knockout mice exhibit significantly better survival rates than wild-type mice in a model of brain edema caused by acute water intoxication induced by focal brain ischemia." (PMID 41329536, 2025). "Thus, cerebral edema caused by cerebral ischemia may relate to the water transportation, in which AQP4 is involved, possibly resulting from the fact that the up-graduation of AQP4 make water transport rapidly from outside the cell and interstitial into cells." (PMID 30233364, 2018). "It was reported that AQP-4 gene silencing mice lack the susceptibility to cytotoxic brain edema caused by bacterial meningitis, and AQP-4 knockout could reduce the rate of water entering brain in cytotoxic edema models, while it would attenuate water transportation from brain in vasogenic edema." (PMID 27833554, 2016). "Also, the down-regulation of AQP4 could amplify a signaling loop associated with vasogenic brain edema." (PMID 23516588, 2013). "Serum levels of 25(OH)D, AQP4, and IL-4, as well as brain edema volume, were measured on days 1, 3, and 7 post-admission." (PMID 42094975, 2026). "Serum 25(OH)D levels were inversely correlated with brain edema volume, while AQP4 and IL-4 levels exhibited a positive correlation (P < 0.05)." (PMID 42094975, 2026). "In our earlier study, we demonstrated the beneficial effects of PCIG in reducing brain edema, which was related to the modulation of polarized AQP4 expression." (PMID 40801636, 2025). "Vasopressin (VP) plays a crucial role in the development of brain injury and has been shown to regulate AQP4 expression in cases of brain edema." (PMID 39944892, 2025).
brain edema (continued). "There is an urgent need to develop specific AQP inhibitors and activators to explore the potential benefits of modulating the functions of AQP1 and AQP4 in the context of brain edema." (PMID 39944892, 2025). "For instance, AQP4 inhibitors have been proposed as potential therapeutic targets to alleviate cerebral edema." (PMID 39768394, 2024). "For instance, in cerebral ischemic stroke and brain edema, reducing AQP4 activity can mitigate symptoms." (PMID 39295943, 2024). "ORI-TRN-002 exhibits superior solubility and overcomes free fraction limitations compared to other reported AQP4 inhibitors, suggesting its potential as a promising anti-edema therapy for treating cerebral edema in the future." (PMID 38255997, 2024). "Previous studies have confirmed the crucial role of AQP4 in astrocytes in facilitating the reabsorption of fluid that has leaked into surrounding areas during the occurrence of vasogenic cerebral edema." (PMID 39148543, 2024). "During excitotoxicity, reactive oxygen species, produced by NADPH‐oxidase 2 (NOX‐2), increases the levels of aquaporin‐4 (AQP4) leading to the rupture of the blood–brain barrier and cerebral edema." (PMID 39496572, 2024). "Others have shown that increases in the protein levels of AQP4 following open-head CCI were a pivotal contributor to cerebral edema, a known sign of inflammation within the brain." (PMID 36909284, 2023). "Due to its characteristic of bidirectional water transport, AQP-4 has the opposite function in cerebral edema via different pathomechanisms." (PMID 37504937, 2023). "In contrast to AQP9, AQP4 appears to collaborate with other astrocytic proteins such as Connexin-43 (Cx43) and the potassium channel Kir4.1 in managing cerebral edema." (PMID 37762642, 2023). "In acute cerebral ischemia or water intoxication, the movement of water facilitated by AQP4 results in cytotoxic brain edema; therefore, in this context reduced AQP4 expression can be beneficial." (PMID 36915214, 2023). "With regard to brain pathophysiology, the functions of AQPs have been worked out most extensively for brain edema, with most of the evidence coming from studies of the AQP4 subtype." (PMID 36768856, 2023). "Drugs like atorvastatin, TGN-020, and goreisan can potentially reduce brain edema through AQP-4 regulation." (PMID 38003477, 2023). "The redistribution of AQP4 appears to be mediated in part by changes of dystroglycan and agrin complexes by matrix metalloproteinases (MMP) 2, 3, and 9 and also affects water flow through AQP4 channels, further contributing to brain edema." (PMID 36768856, 2023). "Studies have revealed that T3 can inhibit the expression of AQP4 in a cerebral infarction model to reduce cerebral edema." (PMID 35111362, 2022). "Our data showed that increased AQP4 protein level was closely correlated with severity of brain edema after TBI." (PMID 35177771, 2022). "Some studies have unveiled that inhibiting astrocyte proliferation and reducing AQP4 depolarization can effectively reduce brain edema." (PMID 35111362, 2022). "First and foremost, several lines of evidence identify the perivascular pool of AQP4 as an influx route for water in models of brain edema." (PMID 35518645, 2022). "Aquaporin-4 plays an important role in the pathogenesis of cerebral edema, as its molecule is the most efficient aqueous channel in this area, regulating its transmembrane flow in astrocytes." (PMID 35627746, 2022). "AQP-4 is a type of membrane protein found extensively in brain tissues that have been found to correlate with the formation of cerebral oedema in brain damage." (PMID 36436500, 2022). "Since brain edema is characterized by the accumulation of water content within the brain parenchyma, our data suggested that blockage of AQP4 with neutralized antibodies effectively ameliorates the development of brain edema after TBI." (PMID 35177771, 2022).